GLI3 (GLI family zinc finger 3)
Diseases named in the same sentence as GLI3 in open-access papers (continued):
Sharing a sentence is not in itself a finding about the gene and the disease.
cancer (continued). "PCR array results comparing CD44high vs CD44low OSCC cell populations using SCC4 and SCC9 cells revealed a greater than 6-fold increase in GLI3 expression in the CD44high cancer stem cell subtype." (PMID 32245491, 2020). "Most studies that have investigated GLI3 in cancer described the cancer supporting role of GLI3 to occur by positively regulating proliferation, survival and invasiveness." (PMID 32245491, 2020). "Several studies found that GLI3 regulates anchorage independent growth, proliferation and migration of cancer cell lines." (PMID 32245491, 2020). "Expression levels of the HH pathway genes, the HH signaling receptors PTCH and SMO, and the target transcription factors GLI2 and GLI3, varied significantly among the cancer cell lines." (PMID 32784501, 2020). "We found higher expression of Patched1 (PTCH1), Shh, Sufu, Smo, Gli1, Gli2 and Gli3 both at mRNA and protein levels than adherent cancer cells." (PMID 32575925, 2020). "Although the role of GLI3 as a negative regulator of HH signaling is well established in the context of normal development, its role in cancer has largely been ignored." (PMID 32784501, 2020). "Future studies focusing on determining the role of GLI3 in the immune response and in cancer will clarify its biological significance and lay the foundation to target this molecule to reprogram immune and cancer cells." (PMID 32245491, 2020). "The HH signaling pathway, acting through transcription factors GLI1, GLI2, and GLI3, has been identified as critical for the initiation and progression of a number of cancers." (PMID 30201866, 2018). "With an increased application of massive parallel sequencing of whole cancer genomes, more mutations in GLI1 and GLI3 have been discovered in breast, colorectal, pancreatic cancers and soft-tissue sarcomas." (PMID 30158435, 2018). "In consistent with cancer relapse, we also found that patients with high expression of GLI1/GLI3 and associated molecules in the primary tumors had worse patient survival." (PMID 28413604, 2017). "We also identified a number of ‘cancer genes'18 as significantly mutated in PDA, including BCLAF1 (5% of cases), IRF6 (4% of cases), FLG (10% of cases), AXIN1 (5% of cases), GLI3 (6% of cases) and PIK3CA (4% of cases)." (PMID 25855536, 2015). "D-finder also pinpointed highly similar D-sites in the paralogous transcription factors Gli1 and Gli2, proteins that (like Gli3) are important in regulators of stem cells and development, and which are dysregulated in several types of cancer." (PMID 20865152, 2010). "At the same time, BPA may weaken the hedgehog signaling suppressor of the fused homolog (SUFU) -GLI family zinc finger 3 (GLI3) pathway by upregulating miR-107, interfering with the DNA repair function of cancer cells." (PMID 38133401, 2023). "Gli3 has also been identified as a key regulator of EMT in various cancers." (PMID 37078230, 2023). "High levels of CCL2 have also been shown to correlate with high cancer occurrence in several cancer types, suggesting Gli3 may play a role in cancer in addition to pathogen-induced inflammation." (PMID 35937499, 2022). "In addition, the majority of studies discussed in this part of the review, describe a role for total GLI3 levels in regulating cancer cell growth and progression." (PMID 32245491, 2020). "Furthermore, miR-494 negative regulation of GLI3 was confirmed in vitro in which inhibition of GLI3 by miR-494 led to a decrease in cell viability and cancer cell migration." (PMID 32245491, 2020). "It is possible the role of GLI3 in cancer is tissue specific." (PMID 32245491, 2020). "The following section summarizes data in which GLI3 was identified as either a pro- or anti-cancerous protein and discusses what is known and what needs to be further investigated to delineate the role of GLI3 in cancer." (PMID 32245491, 2020).
cancer (continued). "GLI3 levels also positively correlated with higher expression of cancer stem cell markers and shRNA-mediated knockdown of GLI3 led to a decrease in the CD44high population (cancer stem cells) while the CD44low population was unaffected in OSCC." (PMID 32245491, 2020). "GLI3 is also involved in tissue development, immune cell development and cancer." (PMID 32245491, 2020). "In addition to regulating proliferation and invasiveness in cancer, GLI3 was also reported to modulate vacuole membrane protein (VMP1), a known regulator of autophagy." (PMID 32245491, 2020). "In addition, recent research shows that negative regulation of GLI3 through microRNA reverses cancerous behavior which emphasizes GLI3 as a potential oncogenic target in cancer therapy." (PMID 32245491, 2020). "Since cancer stem cells are resistant to most chemotherapy due to irregular cell division, GLI3 might be a potential target to sensitize those cells to chemotherapeutic agents." (PMID 32245491, 2020). "For example, since GLI3 negatively regulates S100A9 in OSCC cancer stem cells and this has been shown to induce cell death in cancer cell lines, targeted depletion of GLI3 in OSCC might be an effective strategy in the treatment of OSCC." (PMID 32245491, 2020). "In addition, among deregulated genes, we found GLI3, a negative regulator of the Hedgehog signaling pathway, which is aberrantly activated in cancer." (PMID 31109375, 2019). "Interestingly, Gli1 seems to play a more prominent role in cancer than Gli2 or Gli3, at least based on the number of published studies." (PMID 30754706, 2019). "Future challenges are to understand exactly how Set7 and Gli3 interact and to develop drugs that can block this interaction, which may have the potential to treat cancer." (PMID 27146893, 2016). "Limited Gli-3 mutations are limited and not reported in cancer samples and over expression of Gli-1 is associated with poor prognosis." (PMID 26389956, 2015). "On the other hand, the NMIBC patients receiving Bacillus Calmette-Guerin treatment who carried the GLI3 SNPs rs3801192 and rs6463089 were found to have a higher cancer recurrence rate and shorter recurrence-free survival time compared to those carrying the wildtype genotype." (PMID 23826113, 2013). "Furthermore, Expression of BMI-1, GLI1, GLI2, GLI3 and a list of cancer related microRNAs were also quantified." (PMID 21826251, 2011). "Indeed, a role for GLI3 in cancer progression has been suggested." (PMID 35937499, 2022). "LUAD exhibited a particularly high number of 7 mutated genes with significant co-occurrence with CNAs compared to other cancer types – including EGFR, GATA2, GBA, GLI3, KAT6A, KRAS and NOTCH3." (PMID 41415395, 2025). "The main pathway and genes involved in cancer stem cells include the SHH/GLI-1 signaling pathway, IL6/JAK2/STAT 3 signaling pathway, GLI-1, GLI-3." (PMID 38730691, 2024). "Analysis of cancer genome atlas (TCGA) data has revealed that individuals with CD90+ expression, along with GLI-1 and GLI-3, tend to have a relatively shortened overall survival rate." (PMID 38730691, 2024). "To explore the impact of the GLI family on cancer, we investigated how the GLI1, GLI2, GLI3, and GLI1/2/3 gene sets affect tumors." (PMID 38498906, 2024). "Differential gene expression analysis identified that inflammation‐responsive transcription factors, such as CCL3L1, characterized patients with relapse T‐ALL, along with deregulation of several key cancer regulators such as FAT3, CFTR and GLI3 (Figure SF1A)." (PMID 36819185, 2023). "Therefore, GLI3’s tumorigenic role may be due to its regulation of cancer stem cell survival." (PMID 32245491, 2020). "Since HH signaling is involved in regulating cancer stem cell subtypes in several cancers, it is plausible that SHH regulates this subtype partially via GLI3 in a paracrine manner." (PMID 32245491, 2020). "GLI3, SMURF1, RBPJL, JAG1, LFNG and DTX2 were some of the most amplified genes present in at least 18 cancers." (PMID 31523055, 2019).
cancer (continued). "The quick overview of the Catalogue of Somatic Mutations in Cancer (COSMIC) database shows that there are about 100, 30 and 60 sequence variants that could a priori be considered as pathogenic (nonsense substitutions and frameshift indels) found in GLI1, GLI2 and GLI3, respectively." (PMID 30158435, 2018). "GLI3, ARNT2 and HGF showed predominantly nuclear staining in some cancer cells, while in others, the staining was predominantly cytoplasmic." (PMID 24988459, 2014). "Using several cancer cell lines, we have recently shown that protein phosphatase 2A (PP2A) regulates the subcellular localization and transcriptional activity of GLI3." (PMID 19829694, 2009). "We have recently shown that the subcellular localization and transcriptional activity of GLI3 is regulated by PP2A activity and the MID1-α4 ubiquitin ligase complex in several cancer cell lines with autonomously activated SHH-signaling." (PMID 19829694, 2009). "By utilizing different cancer single-cell datasets, we gained an understanding of the expression distribution of GLI1, GLI2, and GLI3 at the single-cell level and found that GLI1, GLI2, and GLI3 were mainly highly expressed in fibroblasts." (PMID 38498906, 2024). "Thus, miR-506-3p can enhance the efficacy of anti-cancer drugs and can sensitize cancer cells to DNA damage by targeting RAD51, GLI3, and SPHK1." (PMID 33766100, 2021). "GLI3, another member of GLI zinc finger family, was also widely reported in various human cancers." (PMID 33506047, 2021). "Although this resemblance served the purpose of properly separating cancer cell types, mesenchymal cancer cells lack expression of important tRG genes such as AQP4, FAM107A, SOX9, and GLI3, and tRG lack the expression of mesenchymal genes such as CD44 and TIMP1." (PMID 32641768, 2020). "Different expression and activation levels of GLI3-FL regulators (SPOP, androgen receptor, PP2A, CBP, SET7, MED12) or regulators of GLI3-R (PKA, GSK3β, βTrCP) in cancer cells in comparison to healthy cells might also promote cancer cell growth and survival." (PMID 32245491, 2020). "In a variety of mammalian cancer cell lines with self-activated Shh signaling, increasing PP2A activity led to cytosolic retention of full-length Gli3 and its decreased transcription activity, while inhibition of PP2A enhanced Gli3 nuclear accumulation and its transcriptional activity." (PMID 28931407, 2017). "However, no significant increase in Gli1 or Gli3 expression was observed in the whole collection of cancer tissues, possibly because of the extensive individual complexity." (PMID 29722127, 2018).
genetic diseases (2 papers, 2020). "These genetic diseases are known for the formation of an extra digit (postaxial polydactyly) consistent with the Gli3Δ699 mouse model (mice with mutated Gli3 that have similar phenotypes compared to PHS in humans)." (PMID 32245491, 2020). "GCPS, a dominant genetic disorder characterized by polydactyly and craniofacial features, is frequently associated with large deletions or truncating variants which result in loss of GLI3 function." (PMID 33304378, 2020). "In the following section, we provide a more detailed discussion to further elaborate on the role of GLI3 in development and genetic diseases." (PMID 32245491, 2020). "Another clinical condition involving GLI3 is tibial hemimelia, a genetic disorder which leads to hypoplastic or absent tibia." (PMID 32245491, 2020).
infection (2 papers, 2005 to 2022). The state of being infected such as from the introduction of a foreign agent such as serum, vaccine, antigenic substance or organism. "As seen in previous studies, infection of cells with the full-length form of Gli3 was able to repress Gli1-mediated transcription when coexpressed in wild-type cells." (PMID 16254602, 2005). "In the case of the Gli1, Gli2, Gli3, and Gli3R proteins, localization was determined by infection of primary Tg737Δ2–3β-gal mutant and wild-type limb bud cells with adenoviral vectors that express the full-length Gli proteins or the truncated Gli3R fused to GFP." (PMID 16254602, 2005).
adenocarcinoma (1 paper, 2013). A common cancer characterized by the presence of malignant glandular cells. "Upon a specific and important reduction in the mRNA levels of Gli1 that did not affect either Gli2 or Gli3 mRNA levels, cell proliferation and cell viability was decreased in A549 adenocarcinoma cells." (PMID 23667589, 2013).
benign tumors (1 paper, 2009). "HH signaling in GN could be mediated by DHH, which, like GLI1 and GLI3 is differentially expressed in these benign tumors." (PMID 19834598, 2009).
hematologic malignancies (1 paper, 2020). "In addition to the oncogenic role of GLI3 in solid tumors, GLI3 was shown to play a similar role in hematologic malignancies." (PMID 32245491, 2020).
kidney disease (1 paper, 2019). "Among the three cases of unilateral PKD discovered in this study, P45’s case may have been caused by an HNF1B mutation, while P46 and P47 had no gene mutations on the kidney disease panel and P47 had LYZ, FGA, and GLI3 heterozygous mutations on the WES." (PMID 31056860, 2019).
GLI3 also shares sentences with these, for which no sentence is quoted: postaxial polydactyly type A (6 papers); Micropenis (4); anal stenosis (3); preaxial polydactyly type IV (3); pyelonephritis (3); autism spectrum disorder (2); CHARGE syndrome (2); diabetes (2); Down syndrome (2); Feingold syndrome (2); gastric tumors (2); Gorlin syndrome (2); hamartoma (2); Hypertension (2); imperforate anus (2); lung carcinoma (2); microtia (2); oral-facial-digital syndrome (2); proliferative diabetic retinopathy (2); abdominal aortic aneurysm (1); Alagille syndrome (1); alveolar rhabdomyosarcoma (1); anorectal malformation (1); autism (1); autosomal dominant polycystic kidney disease (1); autosomal recessive polycystic kidney disease (1); bacterial infections (1); Bardet-Biedl syndrome (1); basal cell skin carcinoma (1); cannabis dependence (1).
A further 60 diseases each share a sentence with GLI3 in 1 paper.